ABCC5 (ATP binding cassette subfamily C member 5)
Diseases named in the same sentence as ABCC5 in open-access papers (continued):
Sharing a sentence is not in itself a finding about the gene and the disease.
hepatocellular carcinoma (12 papers, 2016 to 2025). A malignant tumor that arises from hepatocytes. "Such as, ABCC5 has been associated with immune infiltration and immune cell differentiation in hepatocellular carcinoma, while ABCA1 deletion has been linked to increased inflammatory cell death." (PMID 40445912, 2025). "Hepatocellular carcinoma displays increased ABCC5 expression, and high ABCC5 expression levels are linked to a poor prognosis in hepatocellular carcinoma patients according to single-cell and pancancer analyses." (PMID 39563862, 2024). "miR-128-3p is known to regulate drug resistance by targeting various genes, including c-Met, MUC1-C, BMI-1, and ABCC5 in hepatocellular carcinoma, glioma, lung cancer, and ovarian cancer." (PMID 36672566, 2022). "Furthermore, Huang and colleagues illustrated that by blocking SLC7A11-induced ferroptosis in hepatocellular carcinoma, ABCC5 aids in the development of sorafenib resistance." (PMID 39315094, 2024). "Therefore, regulating ABCC5 expression to induce ferroptosis is a potential therapeutic strategy for overcoming acquired sorafenib resistance in hepatoma cells." (PMID 37181755, 2023). "The study found that ATP-binding cassette subfamily C member 5 (ABCC5) is highly expressed in hepatocellular carcinoma (HCC)." (PMID 40860808, 2025). "In addition, it was found for the first time in vitro that the expression level of ABCC5 was significantly increased in hepatocellular carcinoma after adipose transformation, and the increased level was positively correlated with the degree of adipose transformation." (PMID 36033523, 2022).
prostate carcinoma (9 papers, 2021 to 2025). A carcinoma that arises from epithelial cells of the prostate gland. "High expression of ABCC5 has previously been linked with prostate cancer progression and with poor progression-free and overall survival." (PMID 36809527, 2023). "The malignant proliferation and migration of prostate cancer caused by ABCC5 was significantly eliminated by inhibiting CDK1 activity." (PMID 33994848, 2021). "ABCC5 was significantly overexpressed in prostate cancer and positively associated with unfavorable clinicopathological features and prognosis." (PMID 33994848, 2021). "ABCC5 facilitates prostate cancer advancement and enzalutamide resistance through the CDK1-mediated AR Ser81 phosphorylation pathway." (PMID 41363115, 2025). "ABCC5 expression is notably increased in prostate cancer compared with benign prostatic hyperplasia." (PMID 39563862, 2024). "The ABCC5 expression data in patients with prostate cancer (PCa) were retrieved from The Cancer Genome Atlas and Gene Expression Omnibus, and their correlation with disease prognosis was analyzed." (PMID 35504877, 2022). "ABCC5 promotes the proliferation, migration, and invasion of prostate cancer tumor cells in vitro and in vivo." (PMID 33994848, 2021). "To further explore the effect of ABCC5 on prostate cancer, we knocked down and overexpressed ABCC5 in two prostate cancer cell lines, C4-2 and VCaP, respectively, and performed a series of tumor cell functional assays." (PMID 33994848, 2021). "The combination of enzalutamide and RO-3306 significantly inhibited the growth of prostate cancer cells with high ABCC5 expression." (PMID 33994848, 2021). "Then, we evaluated the relationship between the expression of ABCC5 and immune cell infiltration in prostate cancer based on the TCGA database." (PMID 33994848, 2021). "In fact, our results showed that high expression of ABCC5 reduced the sensitivity of prostate cancer cells to enzalutamide." (PMID 33994848, 2021). "In conclusion, we found that the expression of ABCC5 was higher in prostate cancer tissue than in normal tissue and that prostate cancer patients with high ABCC5 expression had a poorer prognosis." (PMID 33994848, 2021). "We first demonstrated that ABCC5 was overexpressed in prostate cancer and that a high expression level of ABCC5 resulted in aggressive clinicopathologic features and an unfavorable prognosis." (PMID 33994848, 2021). "In this study, we focused on the specific regulatory mechanism of ABCC5 in prostate cancer progression." (PMID 33994848, 2021). "In CPGEA (p = 0.0091), MSKCC (p = 0.041), and TCGA-PRAD (p < 0.0001), we found shorter progression-free survival (RFS) times in prostate cancer patients with high ABCC5 expression than those with low expression." (PMID 33994848, 2021). "Both in vitro and in vivo experiments confirmed that overexpression of ABCC5 promotes the malignant progression of prostate cancer." (PMID 33994848, 2021). "Our study mainly focused on exploring the downstream regulatory mechanisms of ABCC5 in prostate cancer progression." (PMID 33994848, 2021). "The results of MTS and clone formation assays showed that the proliferation of prostate cancer cells was significantly inhibited and enhanced by ABCC5 knockdown and overexpression, respectively." (PMID 33994848, 2021). "We found that inhibition of CDK1 expression was followed by a significant blockade of the ability of ABCC5 to proliferate and migrate in prostate cancer." (PMID 33994848, 2021). "We found that high expression of ABCC5 significantly accelerated the tumor growth of prostate cancer." (PMID 33994848, 2021). "The procarcinogenic role of ABCC5 in prostate cancer was also confirmed by the results of the rescue assay." (PMID 33994848, 2021). "Expression and prognostic analyses of ABCC5 were performed through bioinformatic methods and immunohistochemistry analyses in multiple public databases as well as in our own prostate cancer cohort." (PMID 33994848, 2021).
prostate carcinoma (continued). "Next, we evaluated the relationship between ABCC5 expression levels and the prognosis of prostate cancer patients in several prostate cancer cohorts, including CPGEA, MSKCC, and TCGA-PRAD." (PMID 33994848, 2021). "The mechanisms of action of ATP binding cassette subfamily C member 5 (ABCC5) in prostate cancer and its relationship with drug resistance are still unclear." (PMID 33994848, 2021). "The biological function of ABCC5 in prostate cancer cells was evaluated by in vitro and in vivo cell proliferation and migration and invasion assays." (PMID 33994848, 2021). "To further validate the effect of ABCC5 on prostate cancer in animals, we chose to perform subcutaneous tumorigenesis experiments using ABCC5-overexpressing VCaP cells injected into immunodeficient nude mice." (PMID 33994848, 2021). "In this study, we discovered the mechanism of ABCC5 in tumor development, namely, promoting malignant phenotypes such as proliferation and migration of prostate cancer by stabilizing CDK1 protein levels and activating ERK signaling pathways." (PMID 33994848, 2021). "The IC50 of enzalutamide in ABCC5-overexpressing prostate cancer cells was 31.2 μM, which was significantly higher than that in the control group." (PMID 33994848, 2021). "Inhibition of CDK1 not only eliminates the cancer-promoting effect of ABCC5 in prostate cancer but also increases the sensitivity of prostate cancer cells to enzalutamide." (PMID 33994848, 2021). "We found that the expression level of ABCC5 was significantly higher in prostate cancer patients with higher GS scores from the CPGEA cohort (p = 0.039), MSKCC cohort (p = 0.046), and TCGA-PRAD cohort (p < 0.001) than those with low scores." (PMID 33994848, 2021). "However, non-drug efflux mechanisms of chemoresistance have also been shown to operate in certain tumours overexpressing ABCC5, especially in the processes that drive prostate cancer metastases." (PMID 41009771, 2025). "ABCC5 emerges as a low critical factor in the progression of prostate cancer." (PMID 40567905, 2025). "Previous reports verified overexpression of ABCC5 can increase the malignancy of prostate cancer." (PMID 36193204, 2022). "Similarly, the invasive ability of prostate cancer cells was suppressed with the downregulation of ABCC5 expression and enhanced with the increase in ABCC5 expression." (PMID 33994848, 2021). "Moreover, ABCC5 mRNA expression was higher in prostate cancer tissues than in matched adjacent normal prostate tissues, as demonstrated in the CPGEA dataset." (PMID 33994848, 2021). "Our previous study found that the immune microenvironment in metastatic and primary sites of prostate cancer is very different, suggesting whether ABCC5 plays a role in the tumor microenvironment." (PMID 33994848, 2021). "Furthermore, to evaluate the expression of ABCC5 at the protein level, we analyzed a total of 149 prostate cancer samples from the Institute of Urology, Peking University prostate cancer dataset (IUPU-PRAD) by immunohistochemistry." (PMID 33994848, 2021). "At present, there are very few studies related to the role of ABCC5 in prostate cancer, and the conclusion that ABCC5 is highly expressed in prostate cancer and correlates with the malignancy of the tumor in the present study fills the gap in this field of research to some extent." (PMID 33994848, 2021). "Similarly, in TCGA-PRAD (p = 0.026) and MSKCC (p = 0.013), prostate cancer patients with high ABCC5 expression also had shorter overall survival times than those with low ABCC5 expression." (PMID 33994848, 2021). "Upregulation of ABCC5 could enhance the cell proliferation, migration, and invasion of prostate cancer in vitro and in vivo." (PMID 33994848, 2021). "Moreover, in enzalutamide-resistant prostate cancer cells, we found that the expression level of ABCC5 was upregulated compared to that in enzalutamide-sensitive tumor cells." (PMID 33994848, 2021).
prostate carcinoma (continued). "In cervical cancer, prostate cancer, and nasopharyngeal carcinoma, FOXM1 caused paclitaxel resistance by modulating the expression of ATP‐binding cassette subfamily C member 5 (ABCC5), in vitro and in vivo studies demonstrate that FOXM1‐specific inhibitors significantly weaken paclitaxel resistance." (PMID 41427004, 2025). "However, a study revealed that ABCC5 causes prostate cancer drug resistance through nondrug efflux mechanisms." (PMID 39563862, 2024). "We performed GO analysis of downstream pathways and GSEA of these differentially expressed genes and found that ABCC5 highly expressed in prostate cancer may act through multiple tumor-related pathways, including the PI3K-Akt and MAPK/ERK signaling pathway and E2F target genes." (PMID 33994848, 2021). "However, ABCC5-mediated enzalutamide resistance did not cause by its classic drug efflux function, which enlightened us to deeper understand the underlying mechanism of hormone therapy and finally crack the drug resistance in prostate cancer." (PMID 35504877, 2022). "Therefore, ABCC5 enhances the expression of phosphorylated P65, which in turn activates transcription by binding to the downstream AR promoter to enhance AR protein expression and pre-mRNA splicing, ultimately promoting enzalutamide resistance in prostate cancer." (PMID 35504877, 2022). "Immediately thereafter, we analyzed transcriptomic data from prostate cancer patients using the WGCNA approach and found that the pink module was highly correlated with ABCC5 expression levels (R = 0.39, p = 4e-19)." (PMID 33994848, 2021). "To fully test our hypothesis, we examined the protein expression levels of ABCC5 and CDK1 in our own prostate cancer cohort and revealed that the protein expression of CDK1 was highly positively correlated with the protein expression of ABCC5." (PMID 33994848, 2021). "To verify whether CDK1 mediates the pro-oncogenic effect of ABCC5 in prostate cancer, we knocked down CDK1 again in prostate cancer cells overexpressing ABCC5 and performed a series of tumor phenotyping experiments." (PMID 33994848, 2021). "To explore the specific mechanism of the cancer-promoting effect of ABCC5 in prostate cancer, we divided the prostate cancer patients in the TCGA-PRAD cohort into an ABCC5 high expression group and an ABCC5 low expression group according to the expression level of ABCC5." (PMID 33994848, 2021).
nasopharyngeal carcinoma (8 papers, 2017 to 2025). A carcinoma arising from the nasopharyngeal epithelium. "Through the expression of ABCC5 (ATP binding cassette subfamily C member 5), FOXM1 overexpression causes paclitaxel resistance in nasopharyngeal carcinoma." (PMID 37569598, 2023). "In our previous study, it was shown that ABCC5 was overexpressed in paclitaxel-resistant nasopharyngeal carcinoma cells, and the expression levels were positively correlated with drug efflux and drug resistance." (PMID 35141332, 2022). "In our previous study, we proved that FOXM1 promotes drug resistance in nasopharyngeal carcinoma cells by regulating ABCC5 gene transcription." (PMID 35141332, 2022). "In nasopharyngeal carcinoma cells, paclitaxel induces ABCC5 expression through the activation of FOXM1, and its blockage re-sensitizes the cells to paclitaxel." (PMID 33632224, 2021).
ovarian carcinoma (8 papers, 2010 to 2024). A malignant neoplasm originating from the surface ovarian epithelium. "High ABCC5 expression is associated with poor overall survival (OS) in ovarian cancer patients." (PMID 39563862, 2024). "And ABCC5 was significantly higher in patients with stage III-IV ovarian cancer than in patients with stage I-II." (PMID 39563862, 2024). "Bioinformatics analysis showed that the overexpression of ABCC5 in ovarian malignant tumours was significantly higher than that in ovarian surface epithelium." (PMID 39563862, 2024). "The up-regulated N-glycosylation level of ABCC5 could play a significant role in multidrug resistance of ovarian cancer, but this hypothesis needs to be validated by further studies." (PMID 28077793, 2017). "In addition, we detected elevated FOXM1 and ABCC5 mRNA levels in paclitaxel-resistant ovarian cancer SKOV3R cells compared with parental SKOV3 cells." (PMID 28277541, 2017).
breast tumor (7 papers, 2012 to 2022). "The role of ABCC5 in the efflux of pemetrexed in MCF-7 cells was established, and ABCC5 expression was inversely correlated with sensitivity to this drug (r = 0.741; p < 0.001) in breast tumour cells obtained from patients." (PMID 35631534, 2022). "In the in vivo study, we observed that ABCC5 affected the sensitivity of pemetrexed in breast tumor-bearing mice, and the tumor volume was much larger in the ABCC5-overexpressing group than in the control group when compared with their own initial volumes (2.7-fold vs. 1.3-fold)." (PMID 33632224, 2021). "In addition, miRNA-128 was significantly reduced in chemoresistant breast tumor-initiating cells (BT-ICs) enriched from breast cancer cell lines and primary breast tumors (P < 0.01), accompanied by an overexpression of Bmi-1 and ABCC5, which were identified as targets of miRNA-128." (PMID 24555688, 2014).
glioma (7 papers, 2010 to 2022). A benign or malignant brain and spinal cord tumor that arises from glial cells (astrocytes, oligodendrocytes, ependymal cells). "ABCC4 and ABCC5 mRNA overexpression and immunostaining has been observed in the glioma cells of astrocytic tumors and in the astrocytic portions of oligoastrocytomas." (PMID 31878061, 2019). "ABCB1/P-gp, ABCG2/BCRP, ABCC1/MRP1, ABCC4/MRP4, and ABCC5/MRP5 up-regulation has been observed in glioma cells at the mRNA and/or protein level; moreover, MRP3 de novo protein expression has also been detected in high grade gliomas (detailed below)." (PMID 31878061, 2019). "Downregulation of ABCG2 expression decreases the chemoresistance of glioblastoma cancer stem cells, and ABCC3 and ABCC5 have been reported to be expressed higher than the other ABCC subfamily members in glioma." (PMID 25605243, 2015). "The high-grade glioma samples showed significantly higher levels of ABCC3/MRP3 and ABCB1/P-gp in the endothelial cells, but higher levels of ABCC1/MRP1, ABCC3/MRP3 and ABCC5/MRP5." (PMID 31878061, 2019).
non-small cell lung carcinoma (7 papers, 2005 to 2023). A group of at least three distinct histological types of lung cancer, including non-small cell squamous cell carcinoma, adenocarcinoma, and large cell carcinoma. "For the target genes, only ABCC5 was identified to have function on gemcitabine sensitivity that related to non-small cell lung cancer." (PMID 35524179, 2022). "It has been reported that ABCC1, ABCC2, ABCC3, ABCC4, ABCC5 and ABCC6 play a significant role in MDR mediated non-small cell lung cancer (NSCLC), breast cancer, prostate cancer, colorectal cancer, ovarian cancer and acute lymphoblastic leukemia (ALL)." (PMID 25191874, 2014).
colorectal cancer (6 papers, 2012 to 2022). A primary or metastatic malignant neoplasm that affects the colon or rectum. "Recently, a report found that single nucleotide polymorphisms of ABCC5 and ABCG1 transporter genes correlated to irinotecan-associated gastrointestinal toxicity in colorectal cancer patients." (PMID 22304828, 2012).
colon cancer (5 papers, 2015 to 2025). "To identify the ABC transporter genes regulated by c-MYC in human colon cancer cells, we investigated the effect of c-MYC knockdown on MDR1, MRP1, ABCB5, ABCC4 and ABCC5 expression levels, which are closely involved in the resistance to chemotherapeutic agents including 5-FU 17–23." (PMID 25689483, 2015).
glioblastoma (5 papers, 2010 to 2025). The most malignant astrocytic tumor (WHO grade IV). "Our data demonstrated that either suppressing miR-381 or enforcing NEFL expression inhibited the expression of multidrug resistance factors (ABCG2, ABCC3, and ABCC5) in glioblastoma cells in the presence of TMZ." (PMID 25605243, 2015). "miRNA-381 may target multidrug resistance proteins (ABCG2, ABCC3, ABCC5) and stemness factors, enhancing glioblastoma sensitivity to temozolomide, while reducing the molecular level of miRNA-318 can lead to drug resistance in glioblastoma." (PMID 40675967, 2025). "A retrospective study showed that the immunohistochemical expression of ABCC5 may have prognostic significance in patients with glioblastoma (GBM)." (PMID 39563862, 2024).
lung carcinoma (5 papers, 2005 to 2024). "Experimental results suggest that increased expression of ABCC5, also known as MRP5, is associated with exposure to platinum drugs in lung cancer in vivo and/or the chronic stress response to xenobiotics." (PMID 15882455, 2005). "In addition, ABCC5 emerged from the databases’ exploration, and we found that it was highly expressed in tumors from patients with lung cancer and strongly correlated with the CSC phenotype." (PMID 39039104, 2024). "Several ABC transporters are linked to lung cancer, such as ABCC1, ABCC3, ABCA3 and ABCC5." (PMID 24625834, 2014). "We aimed to cross-validate these findings on human and murine lung cancer cells and observed that CD133 + CSC differentially expressed higher levels of HA, HAS3, ABCC5, SOX2, and CD47 (p < 0.01)." (PMID 39039104, 2024).
liver cancer (4 papers, 2021 to 2025). An epithelial or non-epithelial malignant neoplasm that arises from the liver. "We observed that the expression of ABCC1 and ABCC5 was associated with the prognosis of liver cancer in both data sets." (PMID 35342392, 2022). "Despite these challenges, ABCC5 and its related genes likely play a crucial role in liver cancer progression through complex regulatory networks, particularly within the TME, which requires further investigation." (PMID 40860808, 2025). "Additionally, the development of ABCC5-targeted inhibitors and the integration of multi-omics studies hold promise for providing a new theoretical foundation for personalized liver cancer treatment." (PMID 40860808, 2025). "Here are a few reports on ABCC5 in HCC, with the existing relevant study indicating that ABCC5 is highly expressed in the liver cancer tissues." (PMID 35342392, 2022). "Furthermore, compared to other ABC transporters like ABCC1 and ABCC4, ABCC5 more directly reflects HCC progression and drug resistance, making it highly valuable for precision medicine and targeted therapies in liver cancer." (PMID 40860808, 2025).